TSPAN1 (tetraspanin 1)
Diseases named in the same sentence as TSPAN1 in open-access papers (continued):
Sharing a sentence is not in itself a finding about the gene and the disease.
breast carcinoma (continued). "However, there are few studies on the role of TSPAN1 in breast cancer." (PMID 34852709, 2021). "In addition, TSPAN1 silencing suppressed tumor growth of breast cancer in mice." (PMID 34852709, 2021). "We thought TSPAN1 could serve as a potential target for breast cancer therapy." (PMID 34852709, 2021). "In addition, TSPAN1 depletion suppressed tumor growth of breast cancer in mice." (PMID 34852709, 2021). "Also, TSPAN1 contributed to tumor growth of breast cancer cells in mice." (PMID 34852709, 2021). "Tspan1 and Tspan15 activate the PI3K/AKT and EGFR/MAPK/ERK pathways, respectively, leading to enhanced proliferation in cholangiocarcinoma and breast cancer." (PMID 38649381, 2024). "We further found that TSPAN1 affected the EMT and mediated the PI3K/Akt pathway in breast cancer cells." (PMID 34852709, 2021). "We further found that TSPAN1 contributed to the EMT and mediated the PI3K/Akt pathway in breast cancer cells." (PMID 34852709, 2021). "In this study, we also noticed the effects of TSPAN1 on the EMT process and PI3K/AKT pathway of breast cancer cells." (PMID 34852709, 2021). "Since previous study indicated the effects of TSPAN1 on EMT process, we then performed Immunoblot assays to detect the effect of TSPAN1 on the EMT of breast cancer cells." (PMID 34852709, 2021). "TSPAN1 promoted EMT and metastasis of cholangiocarcinoma by activating PI3K/AKT pathway, and we also revealed a similar mechanism in breast cancer." (PMID 34852709, 2021). "Through Immunoblot, we found that downregulation of TSPAN1 inhibited the phosphorylation levels of PI3K and AKT, suggesting that TSPAN1 mediated the PI3K/AKT pathway in breast cancer cells." (PMID 34852709, 2021). "Through Immunoblot assays, we further revealed the effects of TSPAN1 on the EMT process and PI3K/AKT pathway in breast cancer cells." (PMID 34852709, 2021). "In our results, the expression levels of TSPAN1, TSPAN13, and TSPAN15 in breast cancer were all increased." (PMID 31182966, 2019). "Tetraspanin 1 (TSPAN1) affects EMT and mediates the PI3K/Akt pathway in breast cancer cells." (PMID 35477364, 2022). "Knockdown of TSPAN1 restrained the EMT process and PI3K/AKT pathway in breast cancer cells." (PMID 34852709, 2021). "Previous study showed that TSPAN1 promoted epithelial-mesenchymal transition (EMT) and metastasis, and whether TSPAN1 could promote breast cancer via regulating EMT needs further study." (PMID 34852709, 2021). "Our TSPAN1 results are consistent with those previously reported, so we speculate that TSPAN13 and TSPAN15 may be potential cancer-related genes for breast cancer." (PMID 31182966, 2019). "Meanwhile, the expression of TSPAN1 was higher in ER-positive and HER2-positive breast cancer." (PMID 31182966, 2019). "However, in breast cancer it is reported that although TSPAN1 gene is amplified in most non-metastasis primary lesions, it is more likely to be obliterated in metastasis matched primary lesions." (PMID 27556508, 2016). "Analyses of the expression levels of all 33 tetraspanins revealed significantly higher expression of TSPAN1, TSPAN15, TSPAN8, TSPAN11, TSPAN29, and TSPAN27 in the breast cancer spheres than in non-CSCs." (PMID 31253779, 2019).
prostate carcinoma (12 papers, 2012 to 2025). A carcinoma that arises from epithelial cells of the prostate gland. "Downregulation of TSPAN1 has been associated with metastasis in prostate cancer, and knockdown inhibited the proliferation of CRC cells and their ability to migrate in an in vitro invasion assay." (PMID 32471474, 2020). "We previously identified the cancer-associated cell migration protein Tetraspanin 1 (TSPAN1) as a clinically relevant androgen regulated target in prostate cancer." (PMID 28701765, 2017). "What's more, on the basis of PTEN classification, TSPAN1 could enhance the prognosis value of PTEN in prostate cancer patients, especially in clinical low risk groups." (PMID 27556508, 2016). "TSPAN1 is upregulated in various cancers and is regulated by androgens, promoting the proliferation and migration of prostate cancer." (PMID 39988626, 2025). "Here, we show that expression of TSPAN1 is controlled by androgens in prostate cancer cells, is upregulated in prostate cancer tissue and is important for prostate cancer cell survival and migration." (PMID 28701765, 2017). "Here we find that TSPAN1 is acutely induced by androgens, and is significantly upregulated in prostate cancer relative to both normal prostate tissue and benign prostate hyperplasia (BPH)." (PMID 28701765, 2017). "We find that while normal expression of TSPAN1 is important for prostate cancer cell viability, induced upregulated expression drives increased cell migration." (PMID 28701765, 2017). "To probe the regulatory mechanism governing TSPAN1-dependent prostate cancer cell motility, we analysed expression of 77 genes with established roles in the epithelial to mesenchymal transition (EMT) and/or cell motility and migration." (PMID 28701765, 2017). "We observed a changing pattern of TSPAN1 expression between primary and metastatic tumours with a striking decrease in TSPAN1 expression in prostate cancer tissue from the metastatic site (p = 5.26E-21)." (PMID 28701765, 2017). "We find TSPAN1 expression in prostate cancer is biphasic, with upregulation at the primary site and downregulation in metastatic lesions." (PMID 28701765, 2017). "We carried out meta-analysis of 1012 prostate tissue samples using data from 14 previously published studies to monitor how expression of TSPAN1 changes in clinical prostate cancer." (PMID 28701765, 2017). "Analysis of previously published RNA-Seq data from before and after 7 days of androgen depletion in prostate cancer patients using Degarelix31 shows a significant reduction in TSPAN1 mRNA indicating a tissue based response." (PMID 28701765, 2017). "We also show for the first time, that TSPAN1 expression in prostate cancer cells controls the expression of key proteins involved in cell migration." (PMID 28701765, 2017). "Our data supports TSPAN1 as an androgen-driven contributor to prostate cancer cell survival and motility, which can control the expression of the mesenchymal proteins Slug and ARF6." (PMID 28701765, 2017). "Our data suggest TSPAN1 is an androgen-driven contributor to cell survival and motility in prostate cancer." (PMID 28701765, 2017). "In conclusion, our study shows that expression of TSPAN1 is controlled by androgens in prostate cancer cells and is upregulated in prostate cancer tissue." (PMID 28701765, 2017). "We found that 11/14 datasets showed significant up-regulation of TSPAN1 mRNA expression in prostate carcinoma versus normal prostate tissue." (PMID 28701765, 2017). "In conclusion, decreased expression of TSPAN1 in prostate cancer led to increased cell proliferation and migration, plausibly through the activation of PI3K/Akt pathway." (PMID 27556508, 2016). "TSPAN1 expression was tested by qPCR in our frozen human prostate cancer samples and paired paracancerous tissues." (PMID 27556508, 2016).
prostate carcinoma (continued). "Three proteins were associated with risk of prostate cancer: GP2, TSPAN1, and FLT3LG [1.29 (1.21–1.36), 1.14 (1.09–1.18), and 0.87 (0.82–0.92)] and three were associated with endometrial cancer: CHRDL2, KLK4, and WFIKKN1 [1.42 (1.21–1.65), 1.41 (1.20–1.65), and 1.42 (1.20–1.68)]." (PMID 38750076, 2024). "TSPAN1, a member of the tetraspanin family, is highly expressed in many types of cancer, and increases cell growth, invasion, and migration in colon, cervical, pancreatic, and prostate cancers." (PMID 33331115, 2021). "In addition, TSPAN1 was under control of androgens and its upregulation increased the motility of prostate cancer cells." (PMID 34852709, 2021). "This set of 700 genes included the gene for the cancer-associated cell migration protein Tetraspanin 1 (TSPAN1) which had not previously been shown to be regulated by androgens in prostate cancer." (PMID 28701765, 2017). "To examine whether TSPAN1 is upstream of key cell signalling pathways in prostate cancer, we tested whether depletion of TSPAN1 influenced PIK3 signalling (detected using phospho-AKT) or RAS/ERK1/2 signalling (detected using phospho-ERK1/2)." (PMID 28701765, 2017). "To investigate why upregulation of TSPAN1 might be important in prostate cancer cells, we created DU145 and PC3 cell lines that over-express TSPAN1 protein." (PMID 28701765, 2017). "TSPAN1 expression analysis by real-time PCR showed that TSPAN1 mRNA was significantly up-regulated in prostate carcinoma samples relative to BPH samples (p = 0.049), and in primary prostate tumour tissue relative to matched normal tissue from the same patient (p = 0.0004)." (PMID 28701765, 2017). "Expression of TSPAN1 in prostate cancer patients was also explored in published datasets." (PMID 27556508, 2016). "Therefore, we decided to investigate clinical significance of TSPAN1 in our postoperative prostate cancer cohort and attempted to explore its function." (PMID 27556508, 2016). "However, according to our knowledge TSPAN1 wasn't reported before in prostate cancer." (PMID 27556508, 2016). "Moreover, TSPAN1 overexpression in prostate cancer cells can inhibit proliferation and migration." (PMID 27556508, 2016). "Here, we show that the Tetraspanin 1 gene (TSPAN1) is regulated by androgens and is significantly upregulated in primary prostate cancer tissue." (PMID 28701765, 2017). "When prostate cancer PC‐3, ovarian cancer SKOV3, and melanoma WM793B cells were exposed to cycling (transient and intermittent) or chronic (prolonged) hypoxia, PC‐3 and SKOV3 cells showed higher TSPAN1 expression levels." (PMID 33331115, 2021). "To test whether changes in the expression of TSPAN1 can influence prostate cancer cell viability, we depleted LNCaP and CWR22RV1 cells of TSPAN1 protein using two independent siRNAs." (PMID 28701765, 2017). "In this study, we first proved that TSPAN1 knockdown increased the phosphorylation level of Akt in vitro and changed cell cycle from phase G1 to S. PI3K/Akt pathway was one of the most prominent alternate pathways in prostate cancer." (PMID 27556508, 2016). "Although its effect on overall survival was not significant, TSPAN1 could be a marker that distinguishes more progressive prostate cancer from the indolent." (PMID 27556508, 2016). "The overlapping TMA data for TSPAN1 between benign and prostate cancer groups presented in this study do not suggest that detection of TSPAN1 alone could be used clinically, but indicate it may still be worthwhile to examine TSPAN1 levels as part of a ‘tetraspanin signature’ in future studies." (PMID 28701765, 2017).
cholangiocarcinoma (8 papers, 2018 to 2024). A carcinoma that arises from the intrahepatic biliary tree (intrahepatic cholangiocarcinoma) or from the junction, or adjacent to the junction, of the right and left hepatic ducts (hilar cholangiocarcinoma). "further demonstrated that in cholangiocarcinoma cells, Tspan1 can drive the EMT process through interactions with integrin α6β1 and the consequent amplification of downstream signaling." (PMID 35280793, 2022). "TSPAN1 could promote cholangiocarcinoma growth, metastasis, and induce epithelial-to-mesenchymal transition (EMT) by interacting with integrin α6β1 to amplify the PI3K/AKT/GSK-3β/Snail/PTEN feedback loop." (PMID 36941633, 2023). "Consistently, Tspan1 was demonstrated to promote the EMT process and metastasis of cholangiocarcinoma via interacting with integrin α6β1 and activating the PI3K/Akt/GSK-3β/Snail/PTEN pathway." (PMID 38389703, 2024). "TSPAN1 reportedly plays a role in increasing epithelial‐to‐mesenchymal transition and metastasis via the PI3K/AKT pathway in cholangiocarcinoma." (PMID 33331115, 2021). "It has also been recently described that TSPAN1 promotes epithelial-to-mesenchymal transition (EMT) and metastasis in a cholangiocarcinoma cancer model." (PMID 33167355, 2020). "Previous study showed that TSPAN1 promoted EMT and metastasis of cholangiocarcinoma via promoting PI3K/AKT pathway, suggesting that TSPAN1 may be a potential therapeutic target for cholangiocarcinoma." (PMID 34852709, 2021). "In cholangiosarcoma and HNSCC models, the interaction of TSPAN1 with integrins has been described." (PMID 33167355, 2020).
cervical cancer (7 papers, 2012 to 2025). A primary or metastatic malignant neoplasm involving the cervix. "Moreover, TSPAN1 expression has been associated with HPV infection in cervical carcinomas, and considered an important diagnostic and prognostic marker, as strong TSPAN1 expression was found in a subset of high-grade cervical cancers and in most of the undifferentiated squamous cell carcinomas." (PMID 33167355, 2020). "Recent research mainly focused on specific cell types and signaling pathways in the cervical cancer TME, such as EPCs and their associated pathways (e.g., TSPAN1, AKR1B10), while studies on other cell types and molecular mechanisms were relatively scarce." (PMID 40777026, 2025). "This study utilized multi-omics approaches to reveal the essential function of TSPAN1 EPCs in the cervical cancer TME." (PMID 40777026, 2025). "A study in cervical cancer excluded a role for TSPAN1 in focal adhesion kinase (FAK), phosphoinositide-3-kinase (PI3K) and in EGFR-dependent signalling to the RAS/ERK pathway, arguing against a role for TSPAN1 as a mediator of cell surface receptor signalling." (PMID 28701765, 2017). "They observed that TSPAN1 gene expression correlated with cell proliferation and suggested that it may be useful as a marker for cervical cancer prognosis." (PMID 30382917, 2018).
colorectal carcinoma (7 papers, 2012 to 2020). A malignant epithelial neoplasm that arises from the colon or rectum and invades through the muscularis mucosa into the submucosa. "As far as TSPAN1 is concerned, 8 data points in 14 sets of data that showed differential expression between colorectal cancer patients and the normal population." (PMID 32694936, 2020). "The expression level of TSPAN1 is increased in colorectal carcinoma and is an independent prognostic factor for the colorectal adenocarcinoma patients." (PMID 31737124, 2019). "In colorectal carcinoma, Tspan1 mRNA is targeted by microRNA-638 suggesting that some tetraspanins are prone to this latter regulatory mechanism." (PMID 28880937, 2017). "miR-638 also inhibits cell proliferation, invasion and regulates cell cycle by suppressing TSPAN1 in human colorectal carcinoma." (PMID 27120793, 2016).
colon cancer (6 papers, 2003 to 2025). "Exosomal tetraspanin 1 (TSPAN1) was shown to be a promising marker for the identification of colon cancer." (PMID 40305328, 2025). "TSPAN1 was found to be upregulated in plasma EVs from colon cancer patients compared to those from healthy controls." (PMID 36941633, 2023). "TSPAN1 and CEA together could provide a novel diagnostic marker for the diagnosis and prognosis of colon cancer." (PMID 40305328, 2025). "Furthermore, TSPAN-1 was found to interact with and stabilize the human thiamine transporter-1 (hTHTR-1) to facilitate thiamine intake in colon cancer and epithelial cells." (PMID 36941633, 2023). "An in vitro study indicated that the downregulation of TSPAN1 significantly inhibited the proliferation and invasion of colon cancer cells, suggesting that TSPAN1 might be a valuable therapeutic target molecule in colon cancer." (PMID 34322151, 2021).
ovarian carcinoma (6 papers, 2014 to 2024). A malignant neoplasm originating from the surface ovarian epithelium. "Upregulated levels of TSPAN1 are considered an early event in the development of high‐risk endometriosis that could progress to ovarian cancer." (PMID 33331115, 2021). "Mucinous and endometrioid subtypes of ovarian cancer tissues have higher TSPAN1 expressions than the serous subtype (n = 72)." (PMID 33331115, 2021). "TSPAN1 is reported to be overexpressed in both ovarian cancer tissue and cell lines." (PMID 35406529, 2022). "TSPAN1 has a different expression level in ovarian cancer subtypes." (PMID 33331115, 2021). "However, it has not been reported that results compared TSPAN1 expression levels in OCCC to other ovarian cancer subtypes." (PMID 33331115, 2021).
esophageal cancer (3 papers, 2020 to 2021). A primary or metastatic malignant neoplasm involving the esophagus. "According to prior research, TSPAN1 is widely expressed in gastric, lung, liver, and esophageal cancers." (PMID 33188589, 2021).
head and neck squamous cell carcinoma (3 papers, 2013 to 2023). A squamous cell carcinoma that arises from any of the following anatomic sites: lip and oral cavity, nasal cavity, paranasal sinuses, pharynx, larynx, and salivary glands. "TSPAN1 is found to be upregulated in cisplatin-resistant head and neck squamous cell carcinoma cells." (PMID 36941633, 2023). "Furthermore, TSPAN1 is found to be elevated in CSCs from head and neck squamous cell carcinoma cells and lead to drug resistance." (PMID 36941633, 2023). "TSPAN1 was found to increase in CDDP-resistant cells, CSCs and biopsies from head and neck squamous cell carcinoma (HNSCC) patients." (PMID 33167355, 2020).
hepatocellular carcinoma (3 papers, 2014 to 2023). A malignant tumor that arises from hepatocytes. "Patients with high TSPAN1 expression had a lower five-year survival rate, and its overexpression increases the risk of death and affects the prognosis of patients with hepatocellular carcinoma." (PMID 37752917, 2023). "We suggest that TSPAN1 may contribute to hepatocellular carcinoma progression by affecting integrin β1." (PMID 37752917, 2023). "Recently, TSPAN1 was reported to accelerate many kinds of cancer progression, especially digestive malignancies such as hepatocellular carcinoma (HCC), pancreatic, gastric, colorectal, and esophageal cancers, and some other non-digestive cancers such as osteosarcoma and cervical cancer." (PMID 30514341, 2018). "Thus TSPAN1 and integrin β1 may play a critical role in hepatocellular carcinoma progression." (PMID 37752917, 2023).
autoimmune hepatitis (2 papers, 2022 to 2025). Hepatitis caused by autoantibodies. "Tetraspanin 1 (TSPAN1) B cells secrete a large number of inflammatory cytokines, which suggests their involvement in autoimmune hepatitis liver injury and its progression." (PMID 40761743, 2025).
endometrial cancer (2 papers, 2011 to 2024). Primary or metastatic malignant neoplasm involving the endometrium (mucous membrane that lines the endometrial cavity). "TSPAN1 is upregulated in oesophageal, ovarian and endometrial cancers." (PMID 21284875, 2011).